IGHV1OR15-1 (immunoglobulin heavy variable 1/OR15-1 (non-functional))
Synonyms: IGHV1/OR15-1
Gene: Immunoglobulin variable (V) gene on chromosome 15 (22,160,431 to 22,160,868, reverse strand). Ensembl gene ENSG00000270505.
Gene Ontology:
Molecular function: antigen binding
Biological process: immunoglobulin mediated immune response
Cellular component: extracellular region; plasma membrane
Homologues: Orthologues: mouse Ighv1-53 (68% identical), mouse Ighv1-64 (68% identical), mouse Ighv1-74 (68% identical), mouse Ighv1-50 (68% identical), mouse Ighv1-55 (67% identical), mouse Ighv1-69 (66% identical), mouse Ighv1-72 (66% identical), mouse Ighv1-26 (64% identical), mouse Ighv1-4 (64% identical), mouse Ighv1-59 (64% identical), mouse Ighv1-62-3 (64% identical), mouse Ighv1-66 (64% identical), and 47 more. Paralogues in human: IGHV1-2 (91% identical), IGHV1-3 (86% identical), IGHV1-46 (84% identical), IGHV1-18 (82% identical), IGHV1-45 (80% identical), IGHV1-24 (79% identical), IGHV1-69 (78% identical), IGHV1-69D (78% identical), IGHV1-58 (76% identical), IGHV1-69-2 (76% identical), IGHV1OR21-1 (76% identical), IGHV1OR15-9 (75% identical), and 65 more.